NOD2 (nucleotide binding oligomerization domain containing 2)
Diseases named in the same sentence as NOD2 in open-access papers (continued):
Sharing a sentence is not in itself a finding about the gene and the disease.
Hepatic steatosis (3 papers, 2020 to 2024). Steatosis is a term used to denote lipid accumulation within hepatocytes. "In addition, NOD2 deficiency caused a slight fat deposition in the liver, i.e., hepatic steatosis, in CTD-fed mice compared to WT mice on CTD." (PMID 32774333, 2020). "HFD-fed Nod2−/− mice had higher body fat percentage and gWAT mass but lower hepatic steatosis compared to HFD-fed WT mice." (PMID 39507249, 2024). "Supporting the importance of NOD2 in non-immune cells, Nod2 KO in the liver after HFD feeding results in augmented liver inflammation, lipid and cholesterol metabolism and increased collagen synthesis, which all promoted liver steatosis and fibrosis." (PMID 37239938, 2023).
hereditary periodic fever syndrome (3 papers, 2008 to 2024). An instance of periodic fever syndrome that is caused by an inherited modification of the individual's genome. "NLRP3, NOD2, MEFV, and PSTPIP1 are the genes responsible for 4 of the syndromes collectively termed hereditary periodic fever syndromes (HPFS)." (PMID 18576390, 2008).
leptospirosis (3 papers, 2017 to 2023). A contagious bacterial infection caused by spirochetes of the genus Leptospira. "In conclusion, host-directed treatment using a TLR2/NOD2 agonist could be envisioned as a novel prophylactic strategy against acute leptospirosis." (PMID 31107928, 2019). "Therefore, in the present study, we hypothesized and showed that pretreatment with CL429, a chimeric TLR2/NOD2 agonist, could mimic the protective effect observed with L plantarum and alleviate the acute phase of leptospirosis due to innate immune memory." (PMID 31107928, 2019). "By extension, we may infer that the positive effect on acute leptospirosis previously observed with oral treatment with Lactobacillus plantarum, which is agonist of both TLR2 and NOD2, was probably due to a trained immunity effect." (PMID 31107928, 2019).
leukemia (3 papers, 2012 to 2024). A malignant (clonal) hematologic disorder, involving hematopoietic stem cells and characterized by the presence of primitive or atypical myeloid or lymphoid cells in the bone marrow and the blood. "NOD2 has a critical role in deterring the recurrence of leukemia after a stem cell transplant." (PMID 38361685, 2024). "While no direct evidence of the involvement of NOD2 variants in leukaemia progression exists, there is much data to show how it can affect the other diseases that are associated with the polymorphisms." (PMID 23119165, 2012).
liver cancer (3 papers, 2020 to 2022). An epithelial or non-epithelial malignant neoplasm that arises from the liver. "We also revealed that inhibition of NOD2 led to the activation of ERK in liver cancer cells." (PMID 36304988, 2022). "Thus, downregulation of NOD2 led to the activation of ERK that might be responsible for the resistance to lenvatinib in liver cancer cells." (PMID 36304988, 2022). "Here we tested the hypothesis that Nod2 protects from high fat diet (HFD)-dependent hepatic cancer." (PMID 33239685, 2020).
MALT lymphoma (3 papers, 2014 to 2022). An indolent, extranodal type of non-Hodgkin lymphoma composed of small B-lymphocytes (centrocyte-like cells). "Patients with MALT lymphomas have a high prevalence of HLA-DQA1*0103, HLA-DQB1*0601 and R702W mutation in the NOD2/CARD15 gene." (PMID 30364585, 2018).
Mediterranean fever (3 papers, 2019 to 2025). "Investigation of 7 cases of PASH and 13 cases of isolated PG revealed multiple mutations in a variety of autoinflammatory genes, including PSTPIP1, Mediterranean fever (MEFV), Nucleotide-binding oligomerization domain-containing protein 2 (NOD2), NLRP3, NLRP12, Lipin 2 (LPIN2)." (PMID 31139187, 2019).
metastatic melanoma (3 papers, 2024). A melanoma that has spread from its primary site to another anatomic site. "MDP treatment was ineffective in Nod2–/– and Ccr2–/– mice with established pulmonary metastatic melanoma colonies, demonstrating the necessity of I-NCMs in MDP-mediated tumor regression." (PMID 39545417, 2024).
multiple myeloma (3 papers, 2020 to 2024). "NOD2/CARD15 variant is correlated to the sensitivity of multiple myeloma bone marrow cells to bortezomib." (PMID 34249967, 2021). "Among all dysregulated immune-related mRNAs, AEN, CD320, FABP5, and GPI were risk factors for multiple myeloma, while CXCL12, IGKC, NOD2, VCAM1, and WNT5A were protective factors for multiple myeloma." (PMID 34249967, 2021).
orofacial granulomatosis (3 papers, 2016 to 2020). "The NOD2 variant which is commonly associated with Crohn’s has not been shown to have any association with orofacial granulomatosis." (PMID 29065902, 2017).
osteoarthritis (3 papers, 2021 to 2025). A noninflammatory degenerative joint disease occurring chiefly in older persons, characterized by degeneration of the articular cartilage, hypertrophy of bone at the margins and changes in the synovial membrane. "Further exploration of the underlying mechanism by which overexpression of NOD2 alleviated osteoarthritis in mice involved immunofluorescent staining." (PMID 38124066, 2023). "This study provides compelling evidence for the pivotal role of NOD2 in OA pathogenesis, demonstrating its capacity to mitigate osteoarthritis by attenuating HMGB1-induced synovial macrophage activation." (PMID 38124066, 2023). "To assess the impact of NOD2 in osteoarthritis, we constructed CIOA mouse model, with detailed grouping outlined in the “Materials and methods” section." (PMID 38124066, 2023). "Interestingly, NOD2 overexpression more significantly retarded the increase in iNOS compared to F4/80, suggesting an association between interrupted M1 phenotype transition and the alleviation of osteoarthritis by NOD2 overexpression." (PMID 38124066, 2023). "Furthermore, in vivo overexpression of NOD2 via lentivirus injection significantly alleviates the severity of osteoarthritis in mice." (PMID 38124066, 2023). "Validation through real-time PCR and Western blotting of synovial tissue corroborated elevated expression of NOD2 and TNF-α in osteoarthritis patients." (PMID 38124066, 2023).
otitis (3 papers, 2016 to 2022). "Recent findings show that NOD2-mediated defensin-β2 production participates in the protection against NTHi-induced otitis." (PMID 33784296, 2021).
otitis media (3 papers, 2014 to 2023). Inflammation of the anatomical structures of the middle ear, which is most often caused by an infectious process. "However, it is poorly understood how NOD2 deficiency affects middle ear inflammation and NTHi clearance from the middle ear cavity." (PMID 24625812, 2014). "Taken together, our findings suggest that a cytoplasmic release of internalized NTHi is involved in the pathogenesis of NTHi infections, and NOD2-mediated β-defensin 2 regulation contributes to the protection against NTHi-induced otitis media." (PMID 24625812, 2014). "In addition, NOD2 plays a role in the immune response to otitis media, the pulmonary immune response, and pathogen clearance." (PMID 37010413, 2023).
periodic fever syndrome (3 papers, 2019 to 2024). Fevers of unknown etiology recurring over months or years. "The NOD2 gene, found on chromosome 16, is implicated in 3 periodic fever syndromes: BS, CD, and YAOS." (PMID 36186408, 2022). "In those clinical scenarios, we suggest testing for a periodic fever syndrome gene panel, including NOD2 whole gene sequencing." (PMID 39372397, 2024).
pneumococcal infection (3 papers, 2018 to 2020). Infections with bacteria of the species streptococcus pneumoniae. "Therefore, high NOD2 expression plays a key role in the pathogenesis of Streptococcus pneumoniae meningitis, and suppressing NOD2 expression may be the new strategy for treating Streptococcus pneumoniae infection." (PMID 30186539, 2018). "Our results showed that NOD2 expression began to increase in the 12 h after Streptococcus pneumoniae infection group, while the remaining inflammatory factors were not obviously increased." (PMID 30186539, 2018).
pyoderma gangrenosum (3 papers, 2008 to 2024). An idiopathic, rapidly evolving, and severely debilitating disease occurring most commonly in association with chronic ulcerative colitis. "Mutations involving different autoinflammatory genes (MEFV, NLRP3, NLRP12, NOD2, LPIN2, and PSTPIP1) have been reported in syndromic HS [pyoderma gangrenosum, acne, and hidradenitis suppurativa (PASH) syndrome] as well as in pyoderma gangrenosum (PG), a prototypic neutrophilic dermatosis." (PMID 32425927, 2020).
respiratory infection (3 papers, 2013 to 2025). "The failure to recapitulate the CD8 T cell defect in the respiratory infection model in mixed bone marrow chimeras in which T cells lack NOD2, but other cells express NOD2, argues that T cell intrinsic NOD2 does not contribute to the CD8 T cell response even in the respiratory infection model." (PMID 23405246, 2013).
Stroke (3 papers, 2019 to 2023). Sudden impairment of blood flow to a part of the brain due to occlusion or rupture of an artery to the brain. "Taken together, our data indicated that ARRB2 deficiency aggravated stroke outcomes induced by NOD2 stimulation after cerebral I/R injury in mice by enhancing inflammation." (PMID 30793522, 2019). "Finally, the in vivo study clearly confirmed that ARRB2 negatively regulated NOD2‐induced inflammatory response, as ARRB2 deficiency exacerbated stroke outcomes and aggravated the NF‐κB signalling pathway induced by NOD2 stimulation after cerebral I/R injury." (PMID 30793522, 2019). "In the middle cerebral artery-occlusion model, the expression of NOD2 is significantly elevated, and ablation of the NOD2 gene reduces stroke size and inflammation as indicated by lowered expression of NF-κB, MAPK, IL-6, and TNF-α." (PMID 34829993, 2021). "Moreover, we further confirmed that ARRB2 negatively regulated NOD2‐induced inflammatory response, as ARRB2‐deficient mice exacerbated stroke outcomes and deletion of ARRB2 aggravated the NF‐κB signalling pathway induced by NOD2 stimulation after cerebral I/R injury." (PMID 30793522, 2019).
acute kidney injury (2 papers, 2018 to 2024). Sudden and sustained deterioration of the kidney function characterized by decreased glomerular filtration rate, increased serum creatinine or oliguria. "It is known that NOD1 and NOD2 contribute to the pathogenesis of various inflammatory diseases, including acute kidney injury." (PMID 29609537, 2018).
acute leukemia (2 papers, 2014 to 2024). A clonal (malignant) hematopoietic disorder with an acute onset, affecting the bone marrow and the peripheral blood. "Our review of 19 extensive cohorts and other studies suggests that NOD2/CARD15 mutations may be a novel risk factor for developing relapse in allogeneic stem cell transplant recipients for acute leukemia." (PMID 38361685, 2024). "NOD2/CARD15 is known to signal natural killer (NK) cells, which may trigger a response to attack acute leukemia." (PMID 38361685, 2024).
acute myeloid leukemia (2 papers, 2017 to 2024). Acute myeloid leukemia (AML) is a group of neoplasms arising from precursor cells committed to the myeloid cell-line differentiation. "Similarly, NOD2 is a surface pattern-recognition receptor that controls inflammatory signals in response to invading bacteria and plays a role in acute myeloid leukemia by inducing the death of abnormal cells." (PMID 38361685, 2024). "In Japanese populations, we revealed that a NOD2 SNP in the NOD domain (R471C) has been associated with acute myeloid leukemia (AML) but not with acute lymphoblastic leukemia." (PMID 29165176, 2017).
allergic asthma (2 papers, 2022 to 2024). A asthma with a basis in a pathological type I hypersensitivity reaction. "Yahia (2021) found that deletion of NOD1 or RIPK2, but not NOD2, inhibited both BAL inflammation and airway responsiveness in response to methacholine in house dust mite (HDM)-induced allergic asthma in mice." (PMID 39507249, 2024).
autoimmune thyroid disease (2 papers, 2009 to 2024). Inflammatory disease of the thyroid gland due to autoimmune responses leading to lymphocytic infiltration of the gland. "The rationale for including such SNPs was to model highly penetrant variants in genes such as NOD2 in CD25 or FLT3 in autoimmune thyroid disease, which play an important role in differentiating these diseases from otherwise genetically related conditions." (PMID 38703768, 2024).
bacterial meningitis (2 papers, 2012 to 2020). Inflammation of the membranes surrounding the brain and spinal cord due to a bacterial infection. "Eleven SNPs in seven genes (TLR2, TLR4, TLR9, NOD1, NOD2, CASP1, and TRAIL) were genotyped in 393 survivors of childhood bacterial meningitis (BM) (327 MM patients and 66 PM patients)." (PMID 22662111, 2012).
bronchiolitis obliterans (2 papers, 2010 to 2024). "This study aims to demonstrate that multivariate analysis proved recipient but not donor NOD2/CARD15 variants to be a novel independent risk factor for BO development, and NOD2/CARD15 typing may help identify patients at increased risk for bronchiolitis obliterans complications." (PMID 38361685, 2024).
chlamydia (2 papers, 2015 to 2025). "Overall, these results demonstrate that induction of aberrance / persistence with the use of PG-targeting antibiotics and iron chelators can drastically impact the degree and kinetics of chlamydia-induced NOD2 signaling." (PMID 40502116, 2025). "Nod1 and Nod2, which also contain the CARDs, were implicated as intracellular sensors that recognize patterns of intracellular pathogens, while expression of both Nod1 and Nod2 in HEp-2 cells were not modified by chlamydial infection based on a DNA microarray analysis (data not shown)." (PMID 26290316, 2015).
Chlamydia infection (2 papers, 2020 to 2025). "This in vitro data suggested that NOD1/NOD2/RIP2 signaling detects a host ER stress response to Chlamydia infection and induces inflammation." (PMID 32487756, 2020). "Overall, these data suggest that RIP2 and NOD1/NOD2 proteins serve to link ER stress induced by Chlamydia infection with the induction of inflammatory responses." (PMID 32487756, 2020). "In this study, we demonstrate that chlamydia infection can be detected by both NOD1 and NOD2 receptors in vitro, but that the kinetics of that signaling differs significantly with NOD2 signaling lagging behind that of NOD1." (PMID 40502116, 2025).
chorioamnionitis (2 papers, 2021 to 2024). A morphologic finding indicating inflammation of the fetal sac membranes. "The expression level of NOD2 mRNA was higher in the chorioamniotic membranes of women with spontaneous preterm labor and acute histologic chorioamnionitis compared to those without acute histologic chorioamnionitis." (PMID 38903689, 2024).
chronic obstructive pulmonary disease (2 papers, 2022 to 2023). A chronic and progressive lung disorder characterized by the loss of elasticity of the bronchial tree and the air sacs, destruction of the air sacs wall, thickening of the bronchial wall, and mucous accumulation in the bronchial tree. "Particularly, NOD2 gene polymorphisms have been associated with development of both Crohn’s disease and chronic obstructive pulmonary disease (COPD), thus favoring the hypothesis of a common genetic susceptibility." (PMID 37835065, 2023).
dengue (2 papers, 2020 to 2024). "The rationale led us to investigate the role of NOD2 during DENV-2-infection in this experimental model, which represents one of the main targets and more significant cells for the immune response to dengue: macrophages." (PMID 38668261, 2024). "Though NOD1 and NOD2 members of the NLR family are activated by specific bacterial peptides, similar to dengue and RSV, we report HEV-induced NLR activation." (PMID 32012176, 2020).
endometriosis (2 papers, 2013 to 2024). The growth of functional endometrial tissue in anatomic sites outside the uterine body. "We also evaluated the association of three polymorphisms in the NOD1, NOD2, and PYDC2 genes with the clinical manifestations of endometriosis." (PMID 40034240, 2024). "However, the potential association between single nucleotide polymorphisms (SNPs) of the NOD1, NOD2, PYDC1, and PYDC2 genes and the predisposition to endometriosis risk remains unexplored." (PMID 40034240, 2024). "The topical delivery of GMDP to the peritoneal macrophages by AMNPs led to the enhance the initially reduced membrane expression of SRs by the macrophages of women with endometriosis, increased NOD2 and RAGE mRNAs expression, and also promoted an increase of the expression of MMP-9 mRNA." (PMID 24455738, 2013).
enteropathy (2 papers, 2020 to 2022). "Here, we report a rare missense mutation affecting the first CARD domain of NOD2 that has been identified in a child with enteropathy and was associated with defective MDP-dependent signaling, abrogated interaction with RIPK2, as well as impaired cytokine responses." (PMID 35273242, 2022). "Since most CD-associated NOD2 variants are located in the LRR domain, the identification of a biallelic missense mutation affecting the CARD domain of NOD2 in a patient with enteropathy prompted us to investigate the signaling and interaction network of the mutant NOD2 protein in greater detail." (PMID 35273242, 2022).
esophageal adenocarcinoma (2 papers, 2023 to 2024). A malignant tumor with glandular differentiation arising predominantly from Barrett mucosa in the lower third of the esophagus. "NOD2 inhibited the proliferation of esophageal adenocarcinoma cells via autophagy, whereas its deficiency promoted colorectal tumorigenesis." (PMID 39353904, 2024). "Previous research has revealed that NOD2 functions as an immunosurveillance factor in certain types of cancers, such as colorectal and esophageal adenocarcinomas, where it is considered protective." (PMID 39353904, 2024). "First, we need to know how NOD2 regulates esophageal adenocarcinoma cells and how NOD2 inhibits EA cell proliferation." (PMID 36316517, 2023). "In vivo, the inhibition of NOD2 overexpression lentivirus on the growth of OE33 cells confirmed the feasibility of this mechanism as a new target for gene therapy of esophageal adenocarcinoma." (PMID 36316517, 2023). "NOD2 can activate autophagy in esophageal adenocarcinoma cells through the ATG16L1 pathway and inhibit cell proliferation." (PMID 36316517, 2023). "Upregulation of NOD2 expression increased the autophagy level of esophageal adenocarcinoma cells via ATG16L1." (PMID 36316517, 2023). "Upregulation of NOD2 expression inhibited the proliferation of esophageal adenocarcinoma cells." (PMID 36316517, 2023). "Therefore, this study mainly explored the possible applications of NOD2’s regulation of autophagy in the treatment of EA, and the results may identify a new therapeutic approach for esophageal adenocarcinoma." (PMID 36316517, 2023). "In vivo experiments: we administered esophageal adenocarcinoma cells to nude mice to form tumors under their skin and then injected the tumors with NOD2 overexpression lentivirus and negative control lentivirus." (PMID 36316517, 2023).
experimental autoimmune encephalomyelitis (2 papers, 2019 to 2024). An autoimmune demyelinating disease of the central nervous system that is produced experimentally in animals by the injection of homogenized brain or spinal cord in Freund's adjuvant. "Another group studying experimental autoimmune encephalomyelitis (EAE, an animal model disease that resembles MS) showed that peptidoglycan works through receptors NOD1, NOD2, and RIP2 and dendritic cells to worsen the disease." (PMID 30718694, 2019). "Finally, in distinct experimental paradigms, including the MS murine model experimental autoimmune encephalomyelitis (EAE), the systemic administration of MDP was shown to foster immune tolerance via the activation of NOD2 in myeloid cells." (PMID 38612613, 2024).